TUG1 (taurine up-regulated 1)
Diseases named in the same sentence as TUG1 in open-access papers (continued):
Sharing a sentence is not in itself a finding about the gene and the disease.
diabetic nephropathy (30 papers, 2017 to 2025). "Furthermore, some lncRNAs participate in the progression of diabetic complications, such as plasma taurine upregulated gene 1 (TUG1) which is associated with the progression of diabetic nephropathy in diabetic rats and Kcnq1ot1 which is involved in the progression of diabetic cardiomyopathy." (PMID 38053839, 2023). "METTL14 orchestrates fibrosis through divergent mechanisms: MAPK/ERK activation via TUG1 regulation in diabetic kidney disease, Sirt1 suppression in focal segmental glomerulosclerosis, and BPTF-driven glycolytic reprogramming in RCC." (PMID 40895041, 2025). "In vitro, the lncRNA TUG1/miR-29c-3p/SIRT1 axis regulates endoplasmic reticulum stress-mediated injury in renal epithelial cells in a diabetic nephropathy model." (PMID 41295241, 2025). "Another work also demonstrated that lncRNA TUG1 reduced accumulation of extracellular matrix by sponging miR-377 and targeting PPARγ in diabetic nephropathy." (PMID 36313695, 2022). "LncRNA TUG1 participated in regulation of podocyte apoptosis via modulation of TRAF5 pathway in diabetic nephropathy rats." (PMID 36313695, 2022). "LncRNA TUG1 influenced podocyte apoptosis via promotion of endoplasmic reticulum stress in diabetic nephropathy progression." (PMID 36313695, 2022). "Recently, TUG1 was also reported to be a regulator in the pathological processes of diabetic nephropathy by affecting the function of mesangial cells and podocyte cells." (PMID 34097717, 2021). "In the present work, we reported a regulatory mechanism of TUG1 in the pathological process of diabetic nephropathy in vitro." (PMID 34097717, 2021). "Taurine upregulated gene 1 (Tug1) was identified as promoting diabetic kidney disease in mitochondria- and endoplasmic-reticulum-dependent mechanisms, respectively." (PMID 32295041, 2020). "For instance, we have recently shown that the lncRNA Tug1 is downregulated in the podocytes of diabetic mice and plays an important role in progression of diabetic nephropathy." (PMID 32467232, 2020). "Studies from our laboratory have shown that the lncRNA Tug1 (taurine upregulated gene 1) is crucial for the progression of diabetic kidney disease, a major microvascular complication of diabetes." (PMID 32467232, 2020). "There is also evidence that TUG1 through a PGC1α-dependent mechanism, contributes to diabetic kidney disease development." (PMID 32368256, 2020). "In diabetic nephropathy (DN), podocyte-specific overexpression of Tug1 improved low PGC-1α expression, and the direct interaction between Tug1 and PGC-1α improved DN-related biochemical and histological features." (PMID 31614978, 2019). "Taurine upregulated gene 1 (Tug1), an evolutionarily conserved lncRNA, regulates mitochondrial bioenergetics in diabetic nephropathy (DN)." (PMID 28835257, 2017). "However, other studies have found that overexpression of TUG1 overexpression can alleviate kidney injury in diabetic nephropathy mice and reduce the inflammatory response and fibrosis of high glucose-stimulated HK-2 cells through the miR-145-5p/DUSP6 axis." (PMID 40755781, 2025). "In addition, lncRNA TUG1 was discovered to regulate mitochondrial bioenergetics via regulation of PGC-1α in podocytes in diabetic nephropathy." (PMID 36313695, 2022). "Moreover, TUG1 reduces the accumulation of extracellular matrix accumulation by antagonizing the effect of miRNA-377 in downregulating PPARγ expression in diabetic nephropathy." (PMID 34097717, 2021). "Also, TUG1 affects the apoptosis of podocytes by modulating pathway in diabetic rats with diabetic nephropathy." (PMID 34097717, 2021).
diabetic nephropathy (continued). "In addition, TUG1 plays critical roles in regulating progression of multiple diseases, such as diabetic nephropathy, atherosclerosis, and myocardial infarction." (PMID 34749662, 2021). "TUG1 modulates mitochondrial bioenergetics in diabetic nephropathy." (PMID 34097717, 2021). "TUG1 regulates miR-29c-3p/SIRT1 and subsequent ERS to relieve high glucose induced renal epithelial cells injury, and suggests a potential role for TUG1 as a promising diagnostic marker of diabetic nephropathy." (PMID 34097717, 2021). "Moreover, overexpression of TUG1 in an animal model of diabetic nephropathy inhibited diabetes-induced ROS formation and albuminuria." (PMID 32368256, 2020). "Thus, our studies further strengthen the relevance of Tug1 and ChREBP in podocyte response to HG and provide strong evidence for considering Tug1 and ChREBP as potential targets for novel diabetic nephropathy therapy." (PMID 32467232, 2020). "Indeed, TUG1 expression was found to be decreased in the context of high glucose levels in a model of diabetic nephropathy." (PMID 33059750, 2020). "TUG1 expression decreased in diabetic podocytes, which caused detrimental metabolic changes in mitochondrial structure and function by regulating PGC-1α expression levels and led to energy depletion and increased ROS generation, ultimately culminating in diabetic kidney disease." (PMID 40176927, 2024). "LncRNA TUG1 (taurine up-regulated gene 1), a lncRNA which locates on human chromosome 22q12.2 and plays an oncogenic role in many kinds of human cancers, was reported to alleviate the histological damage of diabetic nephropathy in diabetic mice by enhancing the expression of PGC-1α in podocytes." (PMID 34097717, 2021). "METTL3 targets TUG1/PGC-1α and ameliorates mitochondrial dysfunction in diabetic nephropathy in an IGF2BP2-dependent manner." (PMID 40685567, 2025). "LncRNA TUG1 inhibited the expression of miR-21 and enhanced the TIMP3 expression, leading to ameliorating diabetic nephropathy." (PMID 36313695, 2022). "With regard to diabetic nephropathy, MALAT1 and TUG1 (Taurine-upregulated gene 1) in animal models and LINC01619 in human renal biopsies, appear to be dysregulated in diabetic podocytopathy." (PMID 34299336, 2021). "Overexpression of TUG1 alleviates extracellular matrix accumulation, including TGF-β1, collagen IV, and fibronectin in diabetic nephropathy through a mechanism dependent on PPARγ." (PMID 32368256, 2020). "A recent study demonstrated that TUG1 inhibited extracellular matrix (ECM) accumulation through post-transcriptional modification of PPARγ, which suggests a new insight for diabetic nephropathy." (PMID 32368256, 2020). "Tug1 (taurine-upregulated gene 1) lncRNA regulates PGC-1α activity, and its overexpression enhanced the mitochondrial bioenergetics in the podocyte of diabetic nephropathy." (PMID 33679710, 2020). "Additionally, lncRNA TUG1 repressed the PI3K/AKT pathway and suppressed the fibrosis and proliferation in mesangial cells in diabetic nephropathy." (PMID 36313695, 2022). "LncRNA TUG1 repressed the PU.1/RTN1 pathway and improved diabetic nephropathy." (PMID 36313695, 2022). "Notably, lncRNA TUG1 affected high glucose-stimulated renal epithelial cell injury via regulation of endoplasmic reticulum stress by targeting miR-29c-3p and SIRT1 in diabetic nephropathy." (PMID 36313695, 2022). "In summary, our study uncovers a lncRNA TUG1—miR-29c-3p - SIRT1 network in regulating high glucose-induced apoptosis via ERS in renal epithelial cells, which can hopefully be beneficial to the pharmacological intervention of diabetic nephropathy." (PMID 34097717, 2021). "One study found that overexpression of a Tug1 RNA isoform lacking ORF1 affects mitochondrial bioenergetics in cultured podocytes derived from a diabetic nephropathy mouse model." (PMID 32894169, 2020).
ovarian carcinoma (28 papers, 2016 to 2025). A malignant neoplasm originating from the surface ovarian epithelium. "For example, TUG1 is highly expressed and associated with poor prognostic markers in bladder, hepatic, colorectal, gastric, renal, and ovarian cancer." (PMID 29657297, 2017). "This study investigated the expression profiles of seven specific long noncoding RNAs (lncRNAs)—SNHG7, TUG1, XIST1, PRLB, TLR8-AS1, ZFAS1, and PVT1—associated with epithelial ovarian cancer and their relationship with drug resistance." (PMID 39992529, 2025). "TUG1 expression is increased in cisplatin-resistant ovarian cancer, consistent with a role for Pol η in modulating the response to cisplatin treatment." (PMID 39457395, 2024). "It has recently been reported that the long non-coding RNA taurine upregulated gene 1 (TUG1) up-regulates Pol η levels in ovarian cancer cell lines by binding to miR487-3p and miR-6088, preventing these miRNAs from targeting POLH mRNA." (PMID 39457395, 2024). "A positive role for TUG1 has also been discovered in pancreatic cancer, esophageal cancer, and ovarian cancer." (PMID 36157241, 2022). "LncRNA TUG1 contributes to autophagy-modulated PTX resistance of ovarian cancer cells by repressing miR-29b-3p." (PMID 35132320, 2022). "lncRNA TUG1 predicted a poor prognosis in epithelial ovarian cancer, promoted cell proliferation, and inhibited apoptosis." (PMID 34039257, 2021). "lncRNA TUG1 acts on amplified in breast cancer 1 (AIB1) to regulate the cell cycle in ovarian cancer." (PMID 34039257, 2021). "lncRNA TUG1 induced autophagy of ovarian cancer cells by targeting miR-29b-3p, which lead to drug resistance to paclitaxel." (PMID 34039257, 2021). "TUG1 is typically upregulated in ovarian cancer and inhibits the onset of apoptosis." (PMID 39912983, 2025). "In this study, it targets the long non-coding RNA TUG1 to inhibit ovarian cancer growth." (PMID 40758729, 2025). "Moreover, in another study, lncRNA TUG1 was found to be overexpressed in ovarian cancer tissue samples and cell lines." (PMID 36899946, 2023). "Interestingly, the expression of TUG1 and miR-29b-3p, one of its potential targets, exhibited an inverse correlation in ovarian cancer tissues and drug resistant cells, suggesting that TUG1 acts as a miR-29b-3p sponge." (PMID 34204094, 2021). "Knockout of lncRNA TUG1 inhibited angiogenesis in ovarian cancer by regulating LRG1." (PMID 34039257, 2021). "LncRNA TUG1 mediates paclitaxel resistance by inducing protective autophagy in ovarian cancer." (PMID 34660304, 2021). "lncRNA TUG1 can be used to predict the resistance of ovarian cancer patients to cisplatin." (PMID 34039257, 2021). "Specifically, TUG1 is upregulated in cisplatin-resistant cells and sponges miR-29b-3p to indirectly upregulate the expression of Beclin1, which increases autophagosome formation in ovarian cancer." (PMID 34660304, 2021). "lncRNA TUG1 promoted the progression of ovarian cancer by targeting the mir-29b-3p/MDM2 axis." (PMID 34039257, 2021). "MiR-582-3p inhibits ovarian cancer survival and migration by targeting AKT/MTOR signaling via lncRNA TUG1." (PMID 35386287, 2022). "One study showed that lncRNA PVT1 was elevated in cisplatin resistant ovarian cancer tissues, while lncRNAs TUG1 and MEG3 were decreased in ovarian cancer patients with cisplatin resistance." (PMID 36105363, 2022). "Knockdown of miR-582-3p promotes the proliferation and migration ability of ovarian cancer and activates the downstream AKT/mTOR signaling pathway, and this promotion is partially abrogated by the knockdown of upstream lncRNA TUG1." (PMID 34793263, 2021). "Previous bioinformatic prediction and validation led us to identify lncRNA taurine up-regulated 1 (TUG1), which is upstream of miR-582-3p as another molecule of potential interest in ovarian cancer." (PMID 34793263, 2021).
ovarian carcinoma (continued). "In the present research, we concentrated on miR-582-3p and aligned it with its upstream regulator lncRNA TUG1 and downstream target, the AKT/mTOR signaling pathway, to explore the behavior of this miRNA in the biology of ovarian cancer." (PMID 34793263, 2021). "Silencing TUG1 decreased Beclin-1 and the conversion of LC3B-I to LC3B-II in ovarian cancer cells." (PMID 36899946, 2023). "The correlations of miR-582-3p expression and its interactions with lncRNA TUG1 with AKT/mTOR signaling and ovarian cancer outcomes suggest that the lncRNA TUG1/miR-582-3p/AKT/mTOR axis may be used as a novel prognostic biomarker and therapeutic target in OC." (PMID 34793263, 2021). "lncRNA TUG1 also regulated aurora kinase A (AURKA), or sponged miR-1299 by up-regulating notch receptor 3(NOTCH3) to promote the proliferation and invasion of epithelial ovarian cancer cells." (PMID 34039257, 2021). "In this study, we focused on miR-582-3p and combined it with its upstream regulator lncRNA TUG1 and potential downstream target AKT/mTOR to explore the malignant biological behavior of this miRNA in regulating ovarian cancer and to analyze the possible molecular mechanisms." (PMID 34793263, 2021). "In ovarian cancer, it has been shown that the lncRNAs HOTAIR, MALAT1, LINC01127, AB073614, ElncRNA1 and ANRIL modulate the PI3K pathways, while LncRNA HOST2 GAS5, TUBA4B modulate the RAS pathway and lncRNAs TUG1, HOXD-AS1, SNHG20 and EBIC modulate the Wnt/β-catenin pathway." (PMID 39912983, 2025).
cervical cancer (24 papers, 2017 to 2024). A primary or metastatic malignant neoplasm involving the cervix. "LncRNA TUG1 expression was upregulated in cisplatin-resistant cervical cancer tissues and linked to a worse prognosis." (PMID 36438563, 2022). "Herein, we report that TUG1 was significantly overexpressed in cervical cancer and it was associated with larger tumor size, advanced international federation of gynecology and obstetrics (FIGO) stage 24, poor differentiation, and lymph node metastasis." (PMID 28088836, 2017). "Therefore, we investigated the biological function of TUG1 via RNA interference‐mediated knockdown (loss‐of‐function approach) using different types of cervical cancer cell lines." (PMID 28088836, 2017). "Taurine upregulated gene 1 (TUG1) is an lncRNA upregulated in cervical cancer, which is closely related to the biological characteristics and poor prognosis of cervical cancer cells." (PMID 36890809, 2023). "It has also been reported that phosphorylated MAPK via lower expression of TUG1 induced promotion of sensitivity of cisplatin in cervical cancer." (PMID 37507864, 2023). "TUG1 depletion inhibited the expression of RFX7 in cervical cancer cells and enhanced cisplatin sensitivity by activation of the MAPK pathway." (PMID 36438563, 2022). "In another clinical study, lncRNA TUG1 is correlated with worse TNM staging in patients with cervical cancer." (PMID 34251066, 2021). "Low expression of lncRNA TUG1 enhanced the sensitivity of cervical cancer to cisplatin by activating the MAPK pathway." (PMID 34039257, 2021). "For instance, lncRNA TUG1 promotes angiogenesis in cervical cancer by an exosomal transport of the lncRNA to the receptor human umbilical vein endothelial cells (HUVECs), thus enhancing their angiogenic capacity." (PMID 32992718, 2020). "A lncRNA, taurine upregulated gene 1 (TUG1), is involved in oncogenesis of various cancer types, including colorectal, pancreatic, and cervical cancer." (PMID 31973032, 2020). "Compared with normal samples, the level of TUG1 was significantly upregulated in all four cervical cancer cell lines, including HPV16(+) SiHa and CaSki cells, HPV18(+) HeLa cells, and HPV(−) C33A cells." (PMID 28088836, 2017). "We observed that TUG1 expression was significantly higher in cervical cancer tissues than in CIN samples (P < 0.001) and normal tissues (P < 0.001)." (PMID 28088836, 2017). "The aim of this research was to investigate the clinical significance and biological functions of TUG1 in cervical cancer." (PMID 28088836, 2017). "In this study, we demonstrated that TUG1 expression was significantly higher in cervical cancer specimens and cervical cancer cell lines than in normal tissues." (PMID 28088836, 2017). "Downregulation of TUG1 significantly reduced cell growth in cervical cancer cells and induced cell apoptosis." (PMID 28088836, 2017). "To determine the expression level of TUG1 in 40 cervical cancer cases, 21 CIN samples ranging from grades I to III, and 19 normal controls, we first employed qRT‐PCR." (PMID 28088836, 2017). "Analysis of the clinicopathological characteristics of patients with cervical cancer revealed that TUG1 upregulation was correlated with larger tumor size, advanced FIGO stage, lower differentiation, and lymph node metastasis." (PMID 28088836, 2017). "This indicates that TUG1 acts as a tumor promoter in cervical cancer by increasing cell proliferation and decreasing cell apoptosis by upregulating Bcl‐2 expression and suppressing the activation of caspase‐3." (PMID 28088836, 2017). "TUG1 was overexpressed in cervical cancer, allowing us to investigate its biological function upon selective inhibition." (PMID 28088836, 2017). "The present findings increase our understanding of the pathogenesis of cervical cancer and implicate TUG1 as a potential new target for the treatment of this disease." (PMID 28088836, 2017).